CD4 (CD4 molecule)
Diseases named in the same sentence as CD4 in open-access papers (continued):
Sharing a sentence is not in itself a finding about the gene and the disease.
HIV-1 infection (continued). "Moreover, a relevant expansion of B cell subpopulations characterized by a CD21lowCD27− phenotype has been recently described in chronically infected patients in advanced stage of HIV-1 infection with a pronounced CD4+ T cell lymphopenia and ongoing HIV-1 replication." (PMID 22474482, 2012). "Thus, the use of anti-apoptotic agents during primary HIV-1 infection may have beneficial effects for preserving the integrity of the CD4+ T-cell pool." (PMID 22511868, 2012). "Importantly, CD4+ T-cells from patients with Aicardi-Goutières Syndrome harboring mutation in the SAMHD1 gene display an increased susceptibility to HIV-1 infection that is not further enhanced by VLP-Vpx-treatment." (PMID 23092122, 2012). "Cytolytic activity against autologous CD4+ cells was found to be abrogated after treatment with an antibody to NKp44L, the cellular ligand of the natural cytotoxicity receptor NKp44, which is specifically induced on CD4+ T cells during HIV-1 infection, in LTNP and HIV progressors." (PMID 22693657, 2012). "During the acute phase of human immunodeficiency virus type 1 (HIV-1) infection, the gastrointestinal-associated lymphoid tissue (GALT) suffers the most substantial immunological and structural damage due to massive elimination of CD4+CCR5+ T-cells, as a result of high levels of viral replication." (PMID 22276176, 2012). "Yet unknown is whether or not the ability of HIV-1 to promote autophagy in bystander CD4+ T cells renders those cells more susceptible to HIV-1 infection." (PMID 22606989, 2012). "Thus, IL-7 might be an effective adjuvant therapy in acute HIV-1 infection, which can protect the pool of CD4+ T cells before it is irreversibly compromised by the action of the virus." (PMID 22511868, 2012). "Synthetic polymeric preparations including a putative V3 consensus sequence (GPGRAF) of HIV-1, were found to inhibit HIV-1 infection by an unknown mechanism; however, it is unlikely that this inhibition was due to competition with gp120 binding to the chemokine receptor or CD4." (PMID 21264298, 2011). "We found that the stimulation of P. marneffe significantly accelerated DC-induced activation of resting CD4+ T cells, which indicates the pivotal importance of DC-driven T-cell activation for the high level of viremia and exacerbation of T-cell depletion in the late stage of HIV-1 infection." (PMID 22110688, 2011). "We demonstrated that the monocyte-derived dendritic cells (MDDCs) could be activated by both thermally dimorphic forms of P. marneffei for significantly promoting HIV-1 trans-infection of CD4+ T cells, while these activated MDDCs were refractory to HIV-1 infection." (PMID 22110688, 2011). "Protease inhibitors, however, require a much higher dose to effectively control HIV-1 infection in macrophages than in CD4+ T-cells, and it is unknown if they achieve the concentrations needed to inhibit macrophage mediated HIV-1 production in compartments such as CNS or testes." (PMID 21489275, 2011). "Therefore, the activation of innate immunity by LPS-mediated TLR4 signaling might attenuate the CD4-independent HIV-1 infection." (PMID 21541353, 2011). "Thus, augmenting hA3G function during acute HIV-1 infection may preserve CD4+ T cell function in GCs and promote HIV-specific antibody development." (PMID 21998583, 2011). "In addition, since A120 mAb treatment increases CXCR4 expression on CD4+ T cells, it may also be possible that the A120 mAb may block X4 HIV-1 infection by interfering with CXCR4 trafficking." (PMID 22018245, 2011). "Overall, these analyses identified a significant number of cis-acting genetic variants influencing gene expression in CD4+ T cells; however, expression polymorphism, genome-wide or among genes that are modulated during HIV-1 infection, did not contribute in a significant fashion to viral control." (PMID 20195503, 2010).
HIV-1 infection (continued). "Finally, we demonstrate that expression of GPI-anchored scFv (X5) in the lipid raft of plasma membrane of human CD4+ T cells confers long-term resistance to HIV-1 infection, HIV-1 envelope-mediated cell-cell fusion, and the infection of HIV-1 captured and transferred by human DCs." (PMID 20923574, 2010). "Therefore, we defined whether expression of the immunoreceptor DCIR on the surface of CD4+ T cells in the context of HIV-1 infection could perhaps be considered as a possible marker of apoptosis for these cells." (PMID 21085612, 2010). "Langerhans cells are susceptible to HIV-1 infection in vitro and can initiate robust infection of memory CD4 T cells, however LC appear to be largely resistant to HIV-1 infection and may instead act to bind and degrade the majority of incoming virions in the subepithelium." (PMID 21994702, 2010). "The study highlights the potential of orally-delivered attenuated Salmonella as mucosal vaccine vectors for HIV-1 Subtype C Gag to induce Gag-specific CD4+ Th1 and Th2 cellular immune responses and antibodies which may be important characteristics required for protection against HIV-1 infection." (PMID 19555490, 2009). "Finally, all subjects in our study were in the chronic stage of HIV-1 infection, when the CD4+ T lymphocyte count almost invariably has decreased significantly from baseline, leaving fewer uninfected cells than in acute infection or after a period of successful antiretroviral therapy." (PMID 19479055, 2009). "Detectable virus-specific CD4+ T cell cytokine responses in HIV-1 infection consist mainly of IFN-γ, whereas in subjects able to control viral replication CD4+ T cells that secrete IL-2 are also detectable, and may be a key component of an effective immune response." (PMID 19352428, 2009). "The ratio of CD4+ T cells to viral loads may be a useful predictor for disease progression of HIV-1 infection, our baseline data did correlate with the disease progression data from the cohort study, the low ratio in HIV-1 mono-infection did progress faster than HIV/HCV group with higher ratio." (PMID 19098990, 2008). "Therefore, our results demonstrated that, at least in unresolving FV infection, CD4+ T cell-mediated bone marrow pathology was triggered by Treg cell insufficiency and suggested that similar mechanisms may operate in HIV-1 infection." (PMID 19006695, 2008). "Thus, TEMRA cells represent the first unique subpopulation of CD4+ T cells that are uniquely resistant to HIV-1 infection and may emerge as a consequence selection during infection." (PMID 17465678, 2007). "However, HIV-1 infection is blocked at an early post-entry step in quiescent CD4+ T cells in vitro." (PMID 17845727, 2007). "However, HIV-1 infection halts prematurely after viral entry into quiescent CD4+ T cells in vitro." (PMID 17845727, 2007). "Therefore such treatment may be considered a more suitable agent to inhibit CD4 dependent HIV-1 infection." (PMID 17187670, 2006). "In vitro, fingolimod decreases HIV-1 infection and viral reservoir (VR) through SAMHD1 phosphorylation inhibition and reducing lymphocyte activation and CD4 expression." (PMID 42234672, 2026). "During HIV-1 infection, latently HIV-1-infected provirus in memory CD4+ T cells contributes to the establishment of reservoir cells that play a role in infectious virus excretion, and are considered major obstacles to HIV-1 eradication." (PMID 40392781, 2025). "We further demonstrate that HIV-1 infection regulates PLIN3 mRNA and protein levels, and knocking down PLIN3 reduces HIV-1 release but enhances virion infectivity in primary CD4+ T cells." (PMID 41085277, 2025). "In this study, we examined how HIV-1 infection affects cellular mRNA m6A levels and characterized the m6A epitranscriptomic profile at single-base resolution in HIV-1-infected primary CD4+ T cells." (PMID 41085277, 2025).
HIV-1 infection (continued). "To better understand the role of CPSF6 in HIV-1 infection, we used CRISPR-Cas9 ribonucleoproteins (crRNPs) to knock-out CPSF6 in primary CD4+ T cells from 4 independent donors." (PMID 41385587, 2025). "By using a chimeric Ad5/F35 adenoviral vector, they successfully delivered the CRISPR/Cas9 system to human CD4+ T cells, efficiently silencing CCR5 expression and protecting these cells against HIV-1 infection with minimal off-target effects." (PMID 40003685, 2025). "In HIV-1 infection, CXCR4 predominantly manifests at the advanced stages, correlating with rapid CD4+ T cell depletion and disease progression." (PMID 40075611, 2025). "Our findings show the importance of m6A RNA modification in HIV-1 infection by regulating host genes like PLIN3 and suggest a unique regulatory mechanism in HIV-1-infected primary CD4+ T cells." (PMID 41085277, 2025). "The current study is the first to reveal the effects of HIV-1 infection on PLIN3 mRNA methylation and expression levels in primary CD4+ T cells." (PMID 41085277, 2025). "However, because in vitro stimulation may alter the susceptibility of each CD4+ T cell subset to HIV-1 infection, the in vitro data may not accurately reflect a virus CD4+ T cell subset targeting in vivo." (PMID 41244297, 2025). "Overall, plasma viral load, blood CD4 + and CD8 + T cells profiles, and immunobiological tests together concluded sustained HIV-1 infection in vehicle-treated mice and reduced burden of viral infection in ART-treated mice." (PMID 40630517, 2025). "γδ T cells display critical role in fighting against HIV-1 infection, by directly killing HIV-1-infected CD4+T cells through the expression of cytotoxic molecules, such as perforin." (PMID 40406103, 2025). "HIV-1 infection increased PLIN3 mRNA level and nuclear accumulation but decreased PLIN3 protein expression in primary CD4+ T cells." (PMID 41085277, 2025). "In parallel to a decline in CD4 + T cells, concomitant increases in CD8 + T cells were noted following HIV-1 infection in all mice." (PMID 40630517, 2025). "Our results highlight the importance of m6A RNA modification during HIV-1 infection and suggest PLIN3 as a regulatory protein of HIV-1 replication in primary CD4+ T cells." (PMID 41085277, 2025). "In differentiated CD4+ macrophage and resting T-cells SAMHD1 activity results in the inhibition of HIV-1 infection through a dNTP blockade." (PMID 38710701, 2024). "Perhaps most notably, and in contrast to HIV-specific CD4+ T cells, cells recognizing cytomegalovirus (CMV) antigens are generally preserved in function, quantity, and proliferative capacity during HIV-1 infection." (PMID 38257808, 2024). "The thymus is an early site for HIV-1 infection: CD4 is expressed not only on mature (CD3+CD4+CD8−) T cells, but also on less mature (CD3−/+ CD4+CD8+) thymocytes and intrathymic T progenitor (ITTP, CD3−CD4+CD8−) cells." (PMID 38903242, 2024). "Following up on the controversy over the role of CD32 in HIV-1 biology, we sought to explore the relationship between HIV-1 infection and CD32 expression on CD4 T cells." (PMID 38579727, 2024). "In order to identify which E3s act in a pro-viral or anti-viral capacity against HIV-1 in primary activated CD4+ T cells, we used an arrayed CRISPR-knockout (KO)-compatible spreading HIV-1 infection assay." (PMID 38411080, 2024). "Beyond its role in immunity, fMLP has demonstrated potential in combating HIV-1 infection by suppressing the expression and activity of CCR5, a vital co-receptor for HIV-1 entry into CD4 + T cells." (PMID 39256638, 2024). "To better understand the role of CPSF6 in HIV-1 infection, we used CRISPR-Cas9 ribonucleoproteins (crRNPs) to knock-out CPSF6 in primary CD4+ T cells from four independent donors." (PMID 39678349, 2024).
HIV-1 infection (continued). "The immune phenotyping and immune functionality analyses ex vivo thereby substantiate the association of the ATG16L1 genotype with phenotypically improved clinical disease outcomes and superior CD4+ and CD8+ T cell immunity in chronic HIV-1 infection." (PMID 38548722, 2024). "To better understand the role of CPSF6 in HIV-1 infection, we used CRISPR-Cas9 gene editing to knock-out CPSF6 in primary CD4 + T cells." (PMID 39678349, 2024). "Our findings thus highlight the potential of pharmaceutically targeting autophagy activity to boost not only CD4+ T cell, but also CD8+ T-cell antiviral immunity in chronic HIV-1 infection." (PMID 38548722, 2024). "Little is known about the impact of HIV-1 infection on the epigenome of other cell types such as B cells, CD8+ T-cells, natural killer (NK) cells, or granulocytes, in addition to monocytes and CD4+ T-cells." (PMID 38466776, 2024). "This study suggested that increase in MM was associated with heightened sensitivity of CD4+T cells to pyroptosis, even in early differentiated and inactivated CD4+T cells, in patients with HIV-1 infection, regardless of whether the patients were on HAART or not." (PMID 38267841, 2024). "In order to assess the relationship between RPLP1 and the disease progression after HIV-1 infection, we further detected the mRNA level of RPLP1 in CD4+ T cells isolated from study participants living with HIV-1." (PMID 38906865, 2024). "Of note, CD4+ TN and TCM cells are regarded as major reservoirs of latent HIV-1 infection in infected individuals on ART." (PMID 36671485, 2023). "In human CD4 + T cell line, expressing of AIMP2-N36 suppressed HIV-1 DNA transcription in single-cycle HIV-1 infection as well as in multiple-round replication studies." (PMID 37933844, 2023). "HIV-1 infection is characterized by continued HIV-1 replication, decline in circulating CD4+ T lymphocytes, and over-activation and exhaustion of CD8+ T lymphocytes." (PMID 38124099, 2023). "One surprising finding in this study is that GPI-scFv X5 not only effectively blocks HIV-1 cell-cell infection of CD4+ cell lines or human primary CD4+ T cells in trans from either iDC or mDC-captured HIV-1, but it also blocks HIV-1 infection of the iDCs." (PMID 37781368, 2023). "The infectious capacity of HIV-1 virions was assayed by infecting permissive CEM.NKR-CCR5 CD4+ T cells with synchronous doses of viral particles produced in HEK-293T cells overexpressing wt-TDP-43 (data on the HIV-1 infection capacity histogram)." (PMID 37108826, 2023). "Early after HIV-1 infection, the intestinal mucosa is subjected to intensive HIV-1 replication, massive CD4+ T-cell depletion, intestinal epithelial barrier breakdown, and microbial translocation into the bloodstream leading to a systemic immune activation." (PMID 37816704, 2023). "Persistent activation of the immune system to HIV-1 infection leads to high levels of CD8+ TL activation, and a progressive decline in CD4+ TL." (PMID 36902388, 2023). "This cell type is a widely applied model cell line for high throughput analysis of HIV-1 infection, because it expresses the HIV-1 receptors CD4 and CCR5 and reports β–galactosidase upon successful infection." (PMID 37612273, 2023). "To examine the role of eCD4-Ig-KiHR and eCD4-Ig-WT to control a spreading T cell-to-T cell HIV-1 infection, we established co-culture model utilizing the Nalm6 B cells and NL4-3 HIV-1 infected SupT CD4+ T cells." (PMID 36879849, 2023). "However, the functional and effector capacity of NK cells against autologous HIV-1 infected CD4+ T cells in MSM at high-risk of HIV-1 infection, has not been elucidated yet, which may clarify their potential in the phenomenon of natural resistance." (PMID 37798386, 2023). "With untreated HIV-1 infection, the number of CD14+ cells was stable, but the number of CD4+ cells declined with time of infection." (PMID 37406092, 2023).
HIV-1 infection (continued). "By example, broadly neutralizing mAbs elicited during chronic HIV-1 infection have been found to target conserved areas on the HIV-1 Env protein such as the trimer apex, CD4 interface, gp41 interface, and glycan-dependent interfaces." (PMID 36792575, 2023). "For example, although it is known that Langerhans cells, DCs and CD4+ T cells are found in the penile foreskin at more superficial surfaces and at higher densities in uncircumcised men, it is only speculated that these are the contributing factors to increased HIV-1 infection in these patients." (PMID 36762762, 2023). "Canonical HIV-1 infection uses both the main HIV-1 receptor, CD4, and the co-receptors, primarily CXCR4 and CCR5." (PMID 37209263, 2023). "Although CD4+ T lymphocytes are considered as the main targets of HIV infection, macrophages also play a significant role in HIV-1 infection and contribute to viral persistence and pathogenesis." (PMID 36988579, 2023). "Other authors have reported that the presence of GalCer on the intestinal epithelial cells of the jejunal tissue, which are GalCer+, CCR5+, CD4−, and CXCR4−, making them permissive to HIV-1 infection." (PMID 37511488, 2023). "We observed that overexpression of wt-TDP-43 did not significantly change the cell-surface expression levels of CD4, CCR5 and CXCR4 molecules (i.e., main receptor and co-receptors for HIV-1 infection, respectively)." (PMID 35682862, 2022). "Therefore, we hypothesize that CCR5 expression, while essential for HIV-1 infection of CD4+ T cells by CCR5-using virus, must be considered in conjunction with other factors, including the cellular subtype and the activation status of a cell, when assessing overall HIV susceptibility." (PMID 36341414, 2022). "CD4+ T cells are markedly depleted over the course of untreated HIV-1 disease and are often considered the primary target of HIV-1 infection." (PMID 36467738, 2022). "Blood CD4+ cell counts and HIV-1 viral load previously determined on the same blood samples to guide clinical care were used as indices of severity of HIV-1 infection." (PMID 36685019, 2022). "The cell surface protein that mediates apoptosis, CD95 (APO-1/Fas), is increased in CD4+ and CD8+ T cell subsets in HIV-1 infection." (PMID 35203323, 2022). "In this mini review, we compare the molecular basis for CD4+ T cell lymphopenia and other effects on the immune system induced by SARS-CoV-2 and HIV-1 infections." (PMID 36313221, 2022). "The rate of CD4+ T-cell decline and disease progression is also slower in HIV-2 compared with HIV-1 infection, accompanied by a lower level of immune activation and more preserved and polyfunctional CD4+ and CD8+ T-cell responses." (PMID 36366545, 2022). "We subsequently investigated the role of KIR2DL5/CD155 interactions in HIV-1 infection, and showed that multiple HIV-1 strains significantly decreased CD155 expression levels on HIV-1-infected primary human CD4+ T cells via a Nef-dependent mechanism." (PMID 35749424, 2022). "Compared to HIV-1 infection, the CD4% has been shown to be higher in early HIV-2 infection with a slower subsequent decline in CD4." (PMID 36366545, 2022). "Another small molecule NBD-556 was the first reported inhibitor against HIV-1 gp120, however, instead of inhibiting the HIV-1 infection it turned out to be a gp120 agonist and lead to the establishment of HIV infection in CD4− CCR5+ cells." (PMID 36422545, 2022). "Our aim in this paper was to develop an HIV-1/HTLV-I co-infection model with humoral immunity and both modes of HIV-1 infection, V-T-C and C-T-C taking into account both latent HIV-1-infected CD4+ T cells and latent HTLV-I-infected CD4+ T cells." (PMID 36016341, 2022). "Selective interaction of the HIV-1 envelope glycoprotein (gp120) with the CD4 molecule which serves as the primary cellular receptor, and one of the chemokine receptors CCR5/CXCR4 or both, constitutes a crucial step in HIV-1 infection." (PMID 36465923, 2022).